CCL2 (C-C motif chemokine ligand 2)
Diseases named in the same sentence as CCL2 in open-access papers (continued):
Sharing a sentence is not in itself a finding about the gene and the disease.
tumor (continued). "Moreover, CCL2, colocalized with β-ARs, was also expressed in both the tumor and immune cells." (PMID 34593796, 2021). "Furthermore, CCL2‐positive TANs were widely distributed in the primary tumour sites and regional lymph nodes, suggesting that they might facilitate tumour progression through CCL2 expression." (PMID 34464477, 2021). "However, acetylated SNAI1 can act as an activator to induce tumor necrosis factor alpha (TNF-α), C-C motif chemokine ligand 2 (CCL2), and C-C motif chemokine ligand 5 (CCL5) gene transcription, which in turn promote carcinoma progression and the recruitment of tumor-associated macrophages (TAMs)." (PMID 34298613, 2021). "In conclusion, based on our data, we hypothesize that the CRC-associated microbiome directly or by releasing bacteria-derived substances (i.e., LPS, ROS, etc.)might promote intestinal lumen inflammation and induce the CCL2 transcription by cells in the tumor microenvironment." (PMID 34639088, 2021). "Our working hypothesis is that the presence of tumor-infiltrating immune cells, here represented as macrophages characterized by the markers CD68, CD163, and CCL2, could be associated with a better prognosis, but that chemotherapy may not add an advantage for prognosis." (PMID 33467469, 2021). "TAFs interact with stromal cells by secreting growth factors, cytokines, and chemokines, including IL6, TGFβ, and CCL2, to amplify immune evasion systems, attracting immunosuppressive cells into the tumor microenvironment, and they also form a network of proinflammatory mediators at the tumor site." (PMID 33384409, 2021). "Thus, CAFs can participate tumor progression and metastasis via CCL2/CCR2 axis." (PMID 34804061, 2021). "Pathogenic microorganisms and tumor cells can be eliminated by M1 macrophages by acute proinflammatory response, immune activation reaction, and cytophagy through the release of proinflammatory factors, such as NO, IL-1β, IL-6, TNF-α, and chemokines such as CCL2, CCL3, CCL5, CXCL9, and CXCL10." (PMID 34506209, 2021). "However, how distant tumor cells use the CCL2 expression in the lung is still unclear." (PMID 34249913, 2021). "Moreover, CAF-derived CCL2 was one of the most probable factors for tumor angiogenesis." (PMID 34386431, 2021). "CCL2 may have autocrine and paracrine, tumour promoting, effects." (PMID 33494138, 2021). "In order to verify the association between CCL2 blood levels and the abundance of bacteria found significantly associated with CRC, we performed linear multiple regression analysis building a model for each of the selected bacteria including the category variable of the tumor presence." (PMID 34639088, 2021). "Notably, Osmrhigh CAFs express higher levels of inflammatory signals such as Il6, Ccl7, Ccl2 and Cxcl1 in animal models of PDA, OSMR is expressed at increased levels in human PDA and is associated with a tumour-promoting immune infiltrate and worse patient outcome." (PMID 34921158, 2021). "As shown in molecular investigations, the monocyte chemo-attractant protein (CCL2), the macrophage colony-stimulating factor (CSF-1), cytokines, and complement components, are well-known specific signaling molecules that recall inflammatory monocytes to the tumor sites." (PMID 34281293, 2021). "Some of these cells secrete chemokines (e.g., CCL2/MCP-1), cytokines (e.g., IL-4, IL-13) and growth factors (e.g., VEGF, CSF1/M-CSF and CSF2/GM-CSF) that trigger the recruitment of monocytes, and can promote cancer progression through the activation of tumor-associated macrophages (TAMs)." (PMID 33710603, 2021). "Therefore, upregulation of GM-CSF, CXCL10, and CCL2 in response to miR-200c restoration may break a vicious paracrine loop between BC cells and macrophages known to support tumor progression." (PMID 34045467, 2021).
tumor (continued). "The expression of the CCL2 gene is controlled by diverse mechanisms including through APOBEC3B-mediated de-repression of epigenetic marks in its promoter, and through Yes-associated protein (YAP) transcriptional regulation, as shown in tumor-initiating cells (TICs)." (PMID 33815418, 2021). "In tumor microenvironment, CCL2 interacts with C-C motif chemokine receptor 2 (CCR2) to mediate chemotaxis of monocytes and tumor associated macrophages (TAMs), which consequently contributes to the shaping of tumor microenvironment and facilitates cancer progression." (PMID 32103760, 2020). "Therefore, the authors concluded that tumour induced factors led to the low HLA-DR expression in the monocyte phenotype, however, Dex reduced CCL2 secretion by the tumour, reducing tumour recruitment of monocytes and resulting in increased peripheral CD14+HLA-DR−/lo monocytes." (PMID 31973059, 2020). "Thus, it is possible that increased macrophage recruitment by Day 3 may involve Ccl2 release by CAFs at a very early stage of tumor formation." (PMID 33329014, 2020). "EV-miR-19 from astrocytes inhibits PTEN expression in metastatic tumor cells, and the tumor cells with PTEN loss recruit IBA1+ myeloid cells to increase proliferation and suppress apoptosis of themselves by secreting chemokine CCL2, thereby promoting brain metastasis in vivo." (PMID 32503543, 2020). "This discrepancy among clinical data suggests that there may be unidentified mechanisms of the CCL2–CCR2 axis with regard to the inhibition of cancer cell activation, and the dynamics of CCL2 in sera and the tumor microenvironment may be different among various cancers." (PMID 33297571, 2020). "Additionally, our findings that CD11b modulation suppresses circulating CCL2 levels in tumor-bearing mice may be an important contributing mechanism defining how CD11b modulation slows tumor growth." (PMID 32528880, 2020). "However, both the CCR2/CCL2 axis and neutrophils are reported to be ‘pro-tumor’ and therefore systemic treatment targeting neutrophils or the CCR2/CCL2 axis in humans may be particularly beneficial in that they decrease tumor size and abrogate CNS dysfunction." (PMID 32391790, 2020). "Moreover, CCL2 recruits Tie2 expressing macrophages to facilitate early tumor cell dissemination." (PMID 32509583, 2020). "Indeed, the blockade of the CCL2/CCR2 axis, in both a preclinical model of CAC and a genetic model of intestinal tumorigenesis (ApcMin mice), leads to the reduction of TAMs in association with significant inhibition of tumor multiplicity and growth." (PMID 32962159, 2020). "Similarly, PMN-MDSC and neutrophils are also recruited to tumours by CCL2 and CCL3." (PMID 32121014, 2020). "Moreover, CCL2 involves tumor cell extravasation through the endothelium." (PMID 33297571, 2020). "Therefore, disruption of the CCL2/TAM axis may be an important component of the mechanism by which CDDO-Me inhibits tumor progression in this model." (PMID 32300202, 2020). "Thus, CCL2 is a major chemoattractant for TAM infiltration of LLC tumor." (PMID 32038501, 2020). "Collectively, these results provide evidence showing that imperatorin may inhibit TGFβ2 expression in cancer cells to suppress CAFs‐secreted CCL2 and the subsequent paracrine effect on endothelial cells and cancer cells, therefore, blocking tumor angiogenesis and invasion." (PMID 32832354, 2020). "Finally, the CCL2 from tumor cells and CCL5 from activated endothelial cells can further recruit the inflammatory monocytes/macrophages to prepare the cellular assembly of CTCs, platelets, neutrophils, endothelial cells and monocytes/macrophages required for efficient extravasation of CTCs." (PMID 33414786, 2020). "CCL2 and CCL7 may also cause infiltration of the tumor by TIL, which has an anti-cancer effect." (PMID 33182504, 2020). "However, whether mTOR cascade affects CCL2-mediated T cells chemotaxis in tumor remains to be further elucidated." (PMID 32483450, 2020).
tumor (continued). "CCL2 also promotes the recruitment of tumor-associated macrophages (TAMs) that may secrete VEGF and the proteolytic enzyme MMP-9, which is involved in the vascularization of tumor tissues." (PMID 32019112, 2020). "Thus, it was hypothesized that 7-isopentenyloxycoumarin could reduce tumor growth and development by the inhibition of angiogenesis and CCL2 release in the tumor microenvironment." (PMID 33327602, 2020). "The combination treatment caused increased secretion of CCL2, CCL21, CXCL1, CXCL2, CXCL5, CXCL9 and CXCL16, whereas the levels of CCL11, CCL17, CCL19, CCL22, CCL25, CCL27 and CX3CL1, which are associated with protumourigenic effects, were decreased in the tumours." (PMID 33014356, 2020). "Interestingly, a hypothesis suggested that tumor cells produce CCL2 to amplify the recruitment of monocytes or macrophages, which might kill tumor cells by producing pro-inflammatory cytokines." (PMID 31991604, 2020). "While previous studies have shown that CCL2 is required for NK cell-mediated clearance of viral infections, information about NK cell chemotaxis in the context of breast tumor challenge is limited compared to T cell trafficking in the disease, and NK trafficking in other tumor types such as colon." (PMID 32040476, 2020). "Also known as MCP-1, CCL2 is a well-known tumor-derived macrophage chemoattractant in the TME." (PMID 33304355, 2020). "Another study showed that MycCaP xenografted immunocompetent FVB mice receiving a diet rich in omega-3 exhibited tumor suppression, as well as lower gene expression of markers for M1 and M2 macrophages, associated cytokines (IL-6, TNF alpha, and IL-10), and the chemokine CCL-2." (PMID 31052319, 2019). "Thus, targeting the CCL-2-CCR-2 axis can reduce numbers of TAMs in the tumor milieu." (PMID 31805946, 2019). "Hence, the depletion of CCL2 results in reduced TAM, pathogenic angiogenesis and tumor progression." (PMID 31540435, 2019). "In addition, tumor presenting high level of CCL2 have significantly poor outcome in GBM patients." (PMID 31207928, 2019). "Interestingly, a knockdown of CCL2/CSF1 in tumor-initiating cells blocked M2 macrophage recruitment and abolished tumorigenesis in an immune system-dependent manner, suggesting that YAP-activated tumor-initiating cells are eliminated without the protection of M2 macrophages." (PMID 31052239, 2019). "Therefore, we decided to test whether deletion of Ccl2 from the TME would result in a lower number of macrophages in tumours." (PMID 31160587, 2019). "Inflammatory CC (CCL2, CCL3, CCL5) and CXC (CXCL1, CXCL2, CXCL5, CXCL6, and CXCL8) chemokines recruit at the tumor site CCR2+ monocytes and CXCR2+ neutrophils that differentiate into tumor associated macrophages (TAMs) and tumor associated neutrophils (TANs), exerting pro- or anti-tumoral role." (PMID 30894861, 2019). "In contrast to CCL2 Can Set Up Effector Molecule Feedback Loops in Tumor-Immune Cell Crosstalk, where CCL2 is involved in promoting tumor growth via suppressing the immune response, a series of older papers demonstrate an inhibitory effect on tumor cell growth of CCL2." (PMID 31921102, 2019). "Moreover, we investigated whether blockade of the CCL2/CCR2 axis by CCR2 specific antagonist (RS504393) could inhibit the tumorigenicity of SACC cells in the xenograft tumor model." (PMID 31024838, 2019). "However, in agreement with previous findings that showed an increase in tumor volume posttreatment, the nCBV was found to be increased in the CCL2-Vehicle group and to be decreased in the CCL2-mNOX-E36 group after treatment compared to the respective tumor volumes before treatment." (PMID 31366997, 2019). "The ability of infiltrated immune cells to promote tumor growth, progression, and immune surveillance may be mediated by several pro-inflammatory cytokines and chemokines, including TNFα, interleukin 17 (IL-17), IL-1, and CCL2 and CCL5." (PMID 30154786, 2018).
tumor (continued). "Furthermore, CCL2 was previously shown to inhibit the generation of tumor-reactive T cells." (PMID 29386061, 2018). "Unlike known MDSCs, MLACs lack the ability to suppress cytotoxic T lymphocytes and differentiate into tumor-associated macrophages (TAMs), but could still directly facilitate tumor growth and angiogenesis through secreting CCL2, CXCL1/2/5, PAI-1, MMPs, and VEGFA." (PMID 29541408, 2018). "ROS/RNS may also inhibit T-cell infiltration into the tumor through inactivating CCL2 by nitration." (PMID 29872437, 2018). "This suggests that MLACs may be recruited by tumor tissue-derived CCL2, which is known to be mainly produced by monocyte/macrophages, suggesting that CCL2 may play a role to maintain a positive feedback loop to establish the immunosuppressive network in tumor tissues." (PMID 29541408, 2018). "Interestingly, we observed strong expression of the inflammasome-induced chemokine CCL2 in association with cholesterol clefts, while GSEA revealed a significant enrichment of an atherosclerotic plaque gene signature in ACP tumours relative to control tissues (NES = 2.12, FDR < 0.001)." (PMID 29541918, 2018). "Thus, MCP-1/CCL2/CCR2 signaling is important in the attraction of MSCs to irradiated tumor cells." (PMID 29615915, 2018). "Furthermore, IL-1β induced CCL2 expression in macrophages and tumor cells." (PMID 30042333, 2018). "In addition, CCL2-neutralizing antibody notably reduced the LNMAT1-transduced tumor burden in the LNs, which led to prolonged survival times of the tumor-bearing nude mice, suggesting that ablation of CCL2 could inhibit LNMAT1-induced LN metastasis." (PMID 30237493, 2018). "The produced CCL2 recruited CD11b+Ly6Chigh inflammatory monocytes to the lungs, where the recruited cells matured into CD11b+Ly6C− IM-like macrophages which produced IL-6 and triggered fibrin deposition, thereby providing the tumor cells with signals to support their survival and growth." (PMID 30597969, 2018). "Interestingly, although B16F10 cells grown in vitro do not express CCL2, immunostaining revealed strong CCL2 expression by developing B16F10 metastatic deposits and surrounding stroma, indicating that the process of tumor formation induces CCL2 expression in these cells." (PMID 30158126, 2018). "The alterations in MDSC and CD8+ T cells ratios within the tumor microenvironment were associated with increased expression of CXCL10, a chemokine that induces CD8+ T cell migration, and a reduction in the expression of CCL2, known to regulate the migration of MDSC." (PMID 29765907, 2018). "Furthermore, the concentration of CCL2 in BC group increases with advancing tumor stage." (PMID 30151375, 2018). "Thus, if on one hand, the abrogation of CCL2 signalling may prevent tumor cell dissemination, on the other hand, it can also impair the recruitment of antitumor immune cell subsets that actively counteract cancer growth and spreading." (PMID 30591657, 2018). "In addition, intranasal delivery of CCL2 increases CD4+ T cell recruitment to the premetastatic niche of the lung, and this correlates with enhanced seeding and growth of tumor cells, while CCL2 shows a potential antitumor activity in tumor-entrained neutrophil-mediated tumor killing in vitro." (PMID 28589151, 2017). "However, the molecular culprits responsible for tumour cell CCL2 secretion and subsequent MPE precipitation remain unknown." (PMID 28508873, 2017). "More importantly, we observe that, expression of CCL2 in both two types’ cells is significantly inhibited upon Kif4A silencing via siRNA, suggesting a potential modulatory-supportive role of this motor protein in establishment of tumor microenvironment in OSCC." (PMID 28533507, 2017). "Since we observed that the PyMT tumor cells make a substantial amount of CCL2, as Granot argued, it could be postulated that CCL2 released into the blood stream by a primary PyMT tumor might impair the outgrowth of tumor cells in the lung after intravenous injection." (PMID 28143493, 2017).
tumor (continued). "It will be important to investigate whether Oligo-Fucoidan impacts the classical activation of M1 macrophages and/or the inhibition of M2 macrophages via inhibiting CCL2 and IL-6 signaling, which modulate anti-inflammation, tumor immunity and tissue remodeling (angiogenesis and metastasis)." (PMID 28928376, 2017). "For instance, the chemokine CCL2 and macrophage colony-stimulating factor were shown to recruit inflammatory monocytes to the tumour site, and then differentiate into TAMs in response to IL-4, IL-10, IL-13 and other cytokines in the tumour microenvironment and promote tumour metastasis." (PMID 29065107, 2017). "Mechanistically, high PIM levels increase the recruitment of tumor/inflammation associated macrophages, MDSCs, mast cells, and neutrophils to the target tissue, by increasing IL-6 locally as well as other cytokines (such as OSM) and probably other chemokines (such as CCL2 and CXCL8)." (PMID 28938604, 2017). "Thus, CCL2 effect seems to be unidirectional from IRISOE tumor cells to macrophages." (PMID 29262555, 2017). "Furthermore, that mutant KRAS-driven MPE is attributed to a CCL2-dependent signalling cascade that is necessary for the sequential translocation of CD11b+Gr1+ cells from the bone marrow to the spleen and the tumour-involved pleural cavity, where, in turn, these cells promote MPE formation." (PMID 28508873, 2017). "Thus it is possible that CCL2 can enhance neutrophil-mediated killing of tumor cells." (PMID 28143493, 2017). "To further examine whether the involvement of CCR2-expressing myeloid cells in radioresistance can be translated into a clinically relevant strategy, we attempted to neutralize CCL2 in tumor studies because it is one of the chemokines proposed to attract CCR2+ cells to tissues and tumors." (PMID 29170400, 2017). "Moreover, CCL2 may recruit other effector cells such as Ly-6Chi inflammatory monocytes or mesenchymal stem cells that modulate tumor growth and progression." (PMID 27820834, 2016). "Notably, the migration to tumor of MDSCs depended mainly on CCL2/CCR2 pathway." (PMID 26992207, 2016). "However a recent report suggests that anti-CCL2 therapy may result in a surge in CCL2 levels and subsequent tumor growth after the treatment phase has ended." (PMID 27058904, 2016). "However, CCL2’s influence on cancer behavior is complex because, in some contexts, it may inhibit tumor growth by attracting tumor-suppressive immune cells." (PMID 27820834, 2016). "However, CCL2 expression was related to tumor differentiation (r = 0.237, p < 0.05)." (PMID 27271610, 2016). "CCL2 levels quantitatively measured in the plasma of patients were significantly higher than those in age- and gender-matched healthy donors (HD); in patients, higher levels were detected in subjects with a high tumor burden than in those with a low tumor burden." (PMID 26684239, 2016). "Because tumor growth can be affected by blood supply, we tested whether angiogenesis was altered in the various genetic backgrounds by examining tissue microarrays and slides using tumors isolated from neu+, neu+Ccl2-/-, and neu+Ccr2-/- mice at different ages." (PMID 27820834, 2016). "Moreover, MCP-1/CCL2-dependent recruitment of monocytic cells has been shown to be important for tumor cell colonization of distant organs in numerous cancers including lungs, bones and liver, although the exact function of the recruited monocytic cells in metastasis is not clear." (PMID 27487154, 2016). "Interestingly, tumor alone produced more CCL2, locally and systemically." (PMID 26158775, 2015). "Thus, we conclude that NF-kB p65 Ser536 plays a significant role in regulating CCL2 expression and the T/E fusion, NF-kB p536 and CCL2 may form a signal pathway that promotes tumor progression." (PMID 25749044, 2015).